RETN (resistin)
Diseases named in the same sentence as RETN in open-access papers (continued):
Sharing a sentence is not in itself a finding about the gene and the disease.
Insulin resistance (continued). "Recent data point to the fact that central resistin induces hepatic insulin resistance by increasing the expression of proinflammatory cytokines, such as IL-6 and TNFα, via an unidentified mechanism mediated by the autonomic nervous system." (PMID 23710116, 2013). "A recent large study involving the Framingham offspring cohort found a significant relationship between insulin resistance and resistin." (PMID 23497617, 2013). "Several studies have reported positive correlations between resistin levels and insulin resistance in vivo and in vitro." (PMID 24455420, 2013). "We will rather focus on the prototypical adipokines (TNF-α, IL-6, leptin, adiponectin, and resistin) highlighting their roles in the development of insulin resistance as well as in immunity and inflammation." (PMID 24455420, 2013). "High levels of leptin and resistin, occurring in obese individuals, promote the development of insulin resistance, whereas adiponectin seems to prevent insulin resistance." (PMID 23825152, 2013). "Correlations between insulin sensitivity, adiposity, and T2DM still remain to be fully revealed, even though resistin has been proposed as a potential link between obesity, insulin resistance, and T2DM with CVD." (PMID 24282409, 2013). "Development of insulin resistance is also affected by several cytokines, including leptin and resistin." (PMID 23762167, 2013). "Although studies in animal models consistently show that resistin induces insulin resistance, evidence for this effect in humans is less clear." (PMID 24245495, 2013). "A study in rodents showed that the infusion of resistin rapidly induced severe hepatic insulin resistance, resulting in a reduced insulin-mediated suppression of gluconeogenesis and increased glycogenolysis." (PMID 23762871, 2013). "This study is aimed to investigate the effect of human resistin on myocyte differentiation and insulin resistance." (PMID 23509781, 2013). "Other studies have suggested a connection amongst resistin, obesity, and insulin resistance, illustrating the importance of adipokines in mammalian physiology." (PMID 23680257, 2013). "Administration of recombinant resistin in rodents impaired hepatic insulin sensitivity and glucose metabolism, and treatment with anti-resistin anti-sense oligonucleotides reversed hepatic insulin resistance." (PMID 23484124, 2013). "It was discovered in 2001 by Dr Mitchell A. Lazar and was called resistin, since mice injected with resistin exhibited insulin resistance." (PMID 23762871, 2013). "HOMA-IR, a strong indicator of the development of insulin resistance, correlated with body and adipose tissue weight, fasting glucose, insulin, C-peptide, leptin and resistin (P < 0.05)." (PMID 23783067, 2013). "Adipokines enlisted in regulation of insulin resistance are adiponectin, leptin, resistin, visfatin, chemerin, TNF-α, IL-1, IL-6, IL-8, IL-10, plasminogen activator inhibitor 1, monocyte chemoattractant protein-1, and retinol binding protein-4." (PMID 24455420, 2013). "Similar to FABPs, these proteins (especially resistin) have been investigated for their role in insulin resistance and diabetes." (PMID 22937046, 2012). "This insulin resistance is mediated in part by placental hormones, including placental growth hormone, human placental lactogen, leptin and resistin." (PMID 22363400, 2012). "In animal models, resistin promotes insulin resistance, while the evidence for this effect in human is less clear." (PMID 22910888, 2012). "Resistin is a cytokine produced by adipose tissue and was originally discovered as a potential mediator of metabolic functions involved in insulin resistance." (PMID 22829946, 2012). "Both leptin and resistin are correlated with insulin resistance and are considered key mediators linking insulin resistance with hepatic steatosis." (PMID 22682228, 2012).
Insulin resistance (continued). "We propose that in this acute model, the GC-dependent metabolic disturbances first appear in adipose tissue overexpressing resistin and in skeletal muscles exhibiting marked insulin resistance." (PMID 22479501, 2012). "It is well-established that insulin resistance in adipose tissue will lead to elevated serum resistin levels and reduced serum adiponectin levels." (PMID 21251282, 2011). "On the other hand, repeated administration of palmitoleic acid down-regulated mRNA expressions of TNFα and resistin, the adipocytokines that have been demonstrated to contribute to insulin resistance." (PMID 21774832, 2011). "Gene expression of resistin, which contributes to insulin resistance, was downregulated by 2.12-fold in the berberine group." (PMID 20953398, 2011). "On the other hand, the administration of recombinant human vaspin improved insulin sensitivity and glucose tolerance, and reverses the expression of those genes that can promote insulin resistance such as leptin, resistin and TNF-α, in diet-induced obese mice." (PMID 21526992, 2011). "Particularly, insulin seems to inhibit resistin secretion, while resistin induces insulin resistance, in an insulin-resistin-insulin sensitivity positive feedback loop." (PMID 21760816, 2011). "It has been well-reported that adiponectin and resistin are promising biomarkers of insulin resistance." (PMID 21251282, 2011). "Correlation was found between HOMA-IR (homeostasis model assessment of insulin resistance) and resistin." (PMID 21912448, 2011). "Serum resistin levels had the strongest correlation with the insulin resistance indexes, plasma glucose and whole blood HbA1C levels." (PMID 21251282, 2011). "Current evidence suggests that, in humans, resistin is more closely related to inflammatory processes than to insulin resistance." (PMID 21691545, 2010). "NF-κB causes insulin resistance by stimulating proinflammatory cytokines like TNF-α, IL-6, IL-1β, and resistin, which in turn activates JNK and NF-κB pathways to create a vicious cycle that will exacerbate tissue damage." (PMID 20508722, 2010). "Retinol-binding protein 4 (RBP4), leptin and resistin are adipocyte-derived biomarkers for insulin resistance and type 2 diabetes." (PMID 20633301, 2010). "Most recently, in “humanized resistin mice”, where human resistin is specifically expressed in macrophages and endogenous retn is disrupted, a high fat diet was found to induce insulin resistance with inflammation of adipose tissue." (PMID 20300528, 2010). "In diabetic or obese subjects, resistin has been shown to be closely correlated to hyperinsulinemia, hyperglycemia, and insulin resistance in several studies." (PMID 19545363, 2009). "Adiponectin, which promotes insulin sensitivity by activation of adenosine monophosphate-activated protein kinase (AMPK) and resistin, which has been identified as an adipocyte specific promoter of insulin resistance in mice." (PMID 19087258, 2008). "Inflammation caused by cardiac surgery increased insulin resistance in a time dependent manner which was paralleled by an induction of cortisol, TNFα, IL6, resistin and leptin while adiponectin serum levels were decreased." (PMID 19087258, 2008). "While resistin's role as an inflammatorymarker in human's and rodent's physiology has been well documented, its role inobesity and insulin resistance in humans is still under debate." (PMID 19125180, 2008). "Non-HDL-c was also significantly associated with insulin resistance (TyG index) and elevated resistin levels, reinforcing its relevance in metabolic dysfunction." (PMID 40662131, 2025). "SdLDL and resistin May have the potential role in predicting cardiometabolic complications (e.g., insulin resistance, dyslipidemia, hypertension)." (PMID 41315571, 2025).
Insulin resistance (continued). "Although it is unknown how resistin directly affects the HPG axis, elevated resistin levels in PCOS potentially exacerbate insulin resistance, amplifying metabolic stress and androgen excess rather than directly altering gonadotropin dynamics." (PMID 40385742, 2025). "They suggested that adults with NF1 could have low levels of leptin and resistin and high levels of adiponectin which could decrease insulin resistance and increase insulin sensitivity." (PMID 40376359, 2025). "Additionally, it has been documented that risperidone induces insulin resistance, which is accompanied by an elevation in resistin levels." (PMID 40234489, 2025). "Moreover, as its name suggests, resistin influences insulin resistance and lipid metabolism, linking it to diabetes mellitus and dyslipidemia." (PMID 40584532, 2025). "The interaction between resistin and TMAO was statistically significant (OR: 1.00, CI: 0.99–1.00, p = 0.004), suggesting that the effects of resistin on insulin resistance may be modified by TMAO levels." (PMID 40077669, 2025). "Additionally, resistin contributes to insulin resistance, which not only reduces muscle glucose uptake but also disrupts anabolic signaling pathways like IGF-1/Akt/mTOR, essential for muscle protein synthesis." (PMID 39983655, 2025). "There are reports that resistin increases insulin resistance in mice." (PMID 40104308, 2025). "Methods: uPTM3-FetA levels in aliquots of 24 h urine specimens, routine laboratory renal, metabolic and inflammatory tests, adipokines (leptin, adiponectin, resistin), and insulin resistance, assessed as the estimated glucose disposal rate (eGDR), were measured in a cohort of 169 adult T1D patients." (PMID 40002573, 2025). "There is a strong correlation between resistin levels and insulin resistance." (PMID 39796247, 2025). "Beyond systemic effects, insulin resistance may impair lung function via adipose tissue dysfunction, which promotes pro-inflammatory adipokines like resistin and reduces anti-inflammatory adiponectin." (PMID 40453581, 2025). "However, overproduction of resistin due to increased adipose tissue reduces adiponectin signaling, leading to insulin resistance and increased production of inflammatory cytokines." (PMID 39334752, 2024). "High plasma resistin concentration has been related to insulin resistance and hepatic steatosis." (PMID 38539808, 2024). "In this study, we searched for a mediator that could explain the differences between mice and humans in the role of resistin to induce insulin resistance." (PMID 39050819, 2024). "High resistin levels induce insulin resistance and exert proinflammatory effects." (PMID 38612899, 2024). "Conversely, resistin, another critical adipokine, promotes insulin resistance and inflammation." (PMID 39596980, 2024). "While resistin was initially thought to play a fundamental role in regulating insulin resistance and inflammation, recent studies have shown a significant association between high levels of resistin and obesity-related diseases, including diabetes, cardiovascular disease, and cancer." (PMID 39184804, 2024). "Importantly, CB1R antagonist treatment significantly reduced resistin-positive cell infiltration, the pathologic changes of mitochondria, and insulin resistance." (PMID 39050819, 2024). "SOCS-3 may mediate resistin-induced insulin resistance and cytokine production, as it is a factor that reduces the insulin response of adipocytes." (PMID 38275812, 2024). "This may also explain the multifaceted role of resistin in chronic inflammation, atherosclerosis, and insulin resistance." (PMID 39184804, 2024). "Another hypothesis is that resistin acts as an insulin antagonist, and thus, insulin resistance might suppress resistin levels, but further research is necessary to elucidate the precise role of resistin in these metabolic alterations." (PMID 38892541, 2024).
Insulin resistance (continued). "Psoriasis promotes systemic inflammation which, in turn, promotes inflammation in adipose tissue, leading to the release of adipokines (resistin, leptin, and visfatin) and proinflammatory cytokines (IL-6 and TNF-α), which are directly linked to increased insulin resistance." (PMID 38473907, 2024). "Additionally, hyperglycaemia and adipokines, such as leptin and resistin, have also been related to the development of insulin resistance in different tissues." (PMID 38473949, 2024). "An abnormal increase of resistin in obese subjects promotes free fat acid release, and increased lipolysis may contribute to the onset of insulin resistance." (PMID 39065709, 2024). "Research on the mechanisms of resistin and insulin resistance is ongoing." (PMID 40302954, 2024). "Resistin is an adipokine that has been studied extensively since its discovery more than 20 years ago; it is considered to be produced by the placenta and is considered to be a regulator of insulin resistance in pregnant women." (PMID 38541892, 2024). "The available data suggest that resistin may exert some influence on insulin resistance during pregnancy, but it is likely to have a secondary role in the pathogenesis of GDM." (PMID 39683486, 2024). "Moreover, several adipokines, such as adiponectin, resistin or visfatin, exert a profound impact on inflammatory processes and insulin resistance development correlated with anovulatory disorders such as polycystic ovary syndrome." (PMID 39273337, 2024). "One hypothesis is that acute elevated levels of resistin is a compensatory response to the accumulation of Aβ; however, chronic levels lead to both brain and peripheral insulin resistance and worsen AD pathology." (PMID 38892118, 2024). "Insulin resistance may be another way that resistin interferes with tumorigenesis because resistin contributes to insulin resistance by interfering with insulin signaling pathways." (PMID 39184804, 2024). "Hence, the increased synthesis of resistin in the placenta is supposed to be responsible for the progressive insulin resistance observed even in healthy pregnancies." (PMID 36674022, 2023). "Additionally, resistin has been shown to induce insulin resistance in mice and directly counter the anti-inflammatory effects of adiponectin." (PMID 37240054, 2023). "The adiponectin, leptin and resistin alternations translate to the worsening of maternal insulin resistance as well as metabolic stress and, in consequence, the promotion of an inflammatory environment, altered placenta functions, and finally, unfavorable conditions for the developing fetus." (PMID 37764842, 2023). "In contrast to its role in insulin resistance or diabetes, resistin may play a more critical role in sepsis." (PMID 37834432, 2023). "In addition, resistin secreted by fat cells can inhibit insulin signaling, leading to insulin resistance and the development of T2DM." (PMID 37560059, 2023). "At the same time, elevated Hcy levels can cause increased secretion of various inflammatory factors, leading to abnormalities in the function of adipose tissue, promoting the production and secretion of resistin, which in turn promotes the occurrence of inflammatory reactions and insulin resistance." (PMID 38028446, 2023). "Leptin and resistin are responsible for enhancing insulin resistance through various means." (PMID 36826001, 2023). "This opinion may be supported by previous findings indicating that chemerin and resistin induce insulin resistance in skeletal-muscle cells at the level of insulin-receptor glucose uptake." (PMID 36830883, 2023). "In contrast, the elevation of chemerin and resistin in our study may have an adverse effect on the progression of insulin resistance in diabetic patients with thyroid dysfunction." (PMID 36830883, 2023). "Resistin is an adipokine that may contribute to the development of insulin resistance, type 2 diabetes, hypertension, dyslipidemia and atherosclerosis." (PMID 36835557, 2023).
Insulin resistance (continued). "Obesity is associated with an increase in the secretion of adipocytokines, such as TNF-α, leptin, resistin, IL-1β or IL-6, by immune cells as well as adipocytes, which leads to the progress of insulin resistance through a number of processes, including the activation of Ser/Thr kinases." (PMID 36826001, 2023). "Overall, although combined training may exert the greatest benefits on resistin levels, RT alone may be an alternative, promoting anti-inflammatory pathways, reducing insulin resistance and improving glucose tolerance through resistin levels reductions." (PMID 36833129, 2023). "Quercetin also had an effect on polycystic ovary syndrome (PCOS), with lower plasma levels of resistin, testosterone, and luteinizing hormone (LH), higher levels of adiponectin, and improved insulin resistance in patients treated with quercetin compared to those treated with placebo." (PMID 37432408, 2023). "Resistin is 10 KDa polypeptide with 114 amino acids in roden, similar in molecular structure to adiponectin and first identified in obese mice, affects in glucose homeostasis and mediate insulin resistance." (PMID 37014444, 2023). "In relation to the metabolic syndrome, other adipokines also act, such as resistin, which facilitates insulin resistance, and adiponectin, which regulates insulin sensitivity and maintains anti-inflammatory effects associated with the modulation of endothelial damage." (PMID 37238961, 2023). "Adipocytes and resident macrophages that have migrated to the adipose tissue produce and secrete adipocytokines, including tumor necrosis factor-α, interleukin-6, resistin, and adiponectin, which are thought to contribute to the development of insulin resistance and T2D." (PMID 37680885, 2023). "Insulin resistance, abnormal metabolism of fat factors [pro-inflammatory adipokines (leptin, resistin, TNF-α), anti-inflammatory adipokine (adiponectin), specific adipokine Sfrp5], and vitamin D deficiency are all possible causes of abnormal blood lipids in visceral obese individuals." (PMID 37674809, 2023). "Then, it could be explained through resistin’s effect in inflammation-induced insulin resistance, probably due to its activity over inflammatory cytokines, such as IL6, IL-12, TNF-α, and (NF-κB)." (PMID 37238961, 2023). "Insulin resistance may also be related to the decreased myogenic differentiation of myoblasts by resistin." (PMID 37853348, 2023). "Both leptin and resistin are secreted proteins, and the levels of leptin and resistin increase when high-fat and high-sugar foods are ingested and in response to other factors, leading to insulin resistance." (PMID 36660274, 2023). "According to studies conducted on diabetic patients, curcuminoids enhance insulin resistance, decrease levels of leptin, resistin, interleukin (IL)-6 IL-1β, and tumor necrosis factor-α, increase the release of adiponectin, and decrease glucose and insulin levels." (PMID 37240220, 2023). "The elevation of LPS depends on TLR to further activate the NF-κB pathway, promoting the release of inflammatory factors, leptin adipose resistin expression, and macrophage M1 proinflammatory phenotype changes, further leading to abnormal insulin resistance and glucose metabolism." (PMID 37072819, 2023). "The results of this meta-analysis suggest that resistin may play a role in insulin resistance, inflammation, and immunology in the pathogenesis of thyroid dysfunction." (PMID 36686437, 2022). "Finally, a positive linear correlation was found among ghrelin and leptin relative to resistin levels in the WT animals, which is related to insulin resistance." (PMID 34935299, 2022). "Moreover, humanized-resistin transgenic mice that lack adipocyte-derived mouse resistin but have macrophages that produce human resistin develop white AT inflammation and insulin resistance after 3 weeks of HFD consumption." (PMID 35909571, 2022).